CXCR2 (C-X-C motif chemokine receptor 2)
Diseases named in the same sentence as CXCR2 in open-access papers (continued):
Sharing a sentence is not in itself a finding about the gene and the disease.
melanoma (continued). "Finally, to define the activity of TFCP2L1 following CXCR2 perturbation, we performed chromatin immunoprecipitation and sequencing analysis (CHIPseq) on B16F0 tumorigenic melanoma cells following treatment with vehicle or SX-682." (PMID 37270599, 2023). "CXCR1 and CXCR2 mRNA exhibited a trend toward increased expression in melanoma compared to nevi, but these differences were not statistically significant." (PMID 37270599, 2023). "Notably, inhibition of both CXCR1 and CXCR2 was necessary to block PMN chemotaxis, highlighting the pleiotropic and redundant potential of melanoma-derived chemokines." (PMID 37525065, 2023). "Previous studies revealed that in melanoma and colorectal carcinoma, CAFs could release C-X-C motif chemokine ligand 5 (CXCL5), which binds to the C-X-C motif chemokine receptor 2 (CXCR2) on cancer cells." (PMID 38111465, 2023). "In contrast to melanoma, anti-CXCR2 therapy did not reduce tumor weight in the mesothelioma mouse model." (PMID 33578808, 2021). "For example, in a melanoma model, it was reported that while TANs did not express CXCR2, BM-neutrophils presented the highest levels of the receptor." (PMID 34680231, 2021). "In malignant melanoma, the expression of CXCL8 and CXCR2 promotes aggressive growth and metastasis." (PMID 33336008, 2020). "Its role in the progression of melanoma mainly depends on its interaction with specific cell surface G protein coupled receptor (GPCR), C-X-C chemokine receptor type 1 (CXCR1) and C-X-C chemokine receptor type 2 (CXCR2)." (PMID 32894090, 2020). "Melanoma grown in mice lacking CXCR2 display reduced inflammation, neutrophil recruitment and tumor growth." (PMID 30899263, 2019). "In a xenograft mouse model of human melanoma, we recently showed that ACT of CXCR2 engineered T cells double the frequency of human CD3+ T cells in s.c. human melanomas, which is substantiated by the identification of CD3+ T cells infiltrating deep into the tumors by IHC." (PMID 30126117, 2018). "Subsequent studies have shown increased infiltration and anti-tumor responses of adoptively transferred mouse and human T cells engineered to express, for instance, CCR4, CXCR2 and CCR2 in transplantable mouse models of Hodgkin’s lymphoma, melanoma and mesothelioma, respectively." (PMID 28923105, 2017). "We show that blocking IL-1R1 signaling or CXCR2 signaling synergizes effectively with MEK inhibition in vivo, suggesting this as a means to delay the onset of resistance that presently too frequently occurs in melanoma patients." (PMID 28450382, 2017). "Similar results were observed in SBC-2-transfected cells (data not shown) Together, these results demonstrate that overexpression of CXCR1 or CXCR2 in SBC-2 and A375P melanoma cells leads to CXCL-8-induced activation of ERK1/2 MAP kinase, which facilitates increased cell growth and motility." (PMID 19401689, 2009). "Therefore, the fact that tumour growth was induced and enhanced by overexpression of CXCR1 or CXCR2 in melanoma cells suggests the importance of CXCR1 and CXCR2 as key determinants of melanoma tumourigenesis and growth." (PMID 19401689, 2009). "In addition to melanoma cells, both CXCR1 and CXCR2 are differentially expressed on endothelial cells." (PMID 19401689, 2009). "CXCR1 or CXCR2 were stably overexpressed in human melanoma cell lines, SBC-2 (non-tumourigenic) and A375P (low-tumourigenic) exhibiting low endogenous expression of receptors." (PMID 19401689, 2009). "CXCR1 and CXCR2 are overexpressed on melanoma cells, but their precise functional role in human melanoma progression is not well established." (PMID 19401689, 2009). "In addition, the inflammatory response pathway was found to be enriched in MES samples as compared to MEL, accompanied by significantly high expression of CXCL1 and its receptor, CXCR2, as well as chemokine receptors CCR4 and CCR6, in melanomas characterised by the invasive gene signature." (PMID 36765773, 2023).
melanoma (continued). "Furthermore, in animal experiments with melanoma and CRC, the up-regulated expression of tumor PD-L1 induced by CAFs was reversed after silencing CXCL5’s receptor CXCR2.This suggests that the CXCL5-CXCR2 axis may be a promising therapeutic target." (PMID 36759842, 2023). "Moreover, CXCR2 depletion has been shown to have a negative effect on tumor growth and angiogenesis in a mouse model of lung cancer and melanoma." (PMID 35158807, 2022). "Studies with neutralizing antibodies to either CXCR1 and CXCR2 showed inhibition of MC proliferation and invasive potential whereas in athymic nude mice oral administration of CXCR1/2 antagonists, inhibited the growth and angiogenesis of implanted human melanoma tumors." (PMID 35011682, 2021). "Aside from its direct effect on melanoma cells, CXCL8, along with other ligands of CXCR1 and CXCR2, namely CXCL1-3 and CXCL5-7, recruit innate cells, most notably neutrophils, which express the receptors CXCR1 and CXCR2 and are the “first responders” to tissue injury and damage." (PMID 34830780, 2021). "Furthermore, BRAFi treatment-induced tolerance in melanoma could be shown to result from a cytokine-signaling network involving TAM-derived IL-1β and CAFs derived C-X-C motif chemokine receptor 2 (CXCR2) ligands." (PMID 30042333, 2018). "However, the functional significance of CXCR1 and CXCR2 and its ligand CXCL-8 in melanoma progression remains unclear." (PMID 19401689, 2009). "However, we did not observe a difference in ERK1/2 phosphorylation between melanoma cells expressing CXCR1 or CXCR2, which further suggests the involvement of both receptors in the MAPK pathway." (PMID 19401689, 2009). "The ABCB5 drug efflux transporter, a marker for slow-cycling melanoma cells, was shown to be related to the expression of CXCR1 but not CXCR2." (PMID 36831112, 2023). "Interestingly, we found that PMN-MDSC infiltrating mesothelioma showed much lower level of CXCR2 expression than in melanoma that might explain the lack of anti-tumor effect of CXCR2 blockade, indicating that the beneficial effect of such therapy might be successful not in all cancer types." (PMID 33578808, 2021). "For instance, it was observed that many melanomas had a high production of the chemokine CXCL1, but that its receptor CXCR2 was not profoundly expressed on T lymphocytes." (PMID 33287413, 2020). "Indeed, when T-cells were engineered to express CXCR2, their recruitment to B16 murine melanoma overexpressing CXCL1 was increased, resulting in greater tumour regression compared to T-cells lacking CXCR2 overexpression." (PMID 28435677, 2017).
Sepsis (76 papers, 2010 to 2025). Sepsis is defined as life-threatening organ dysfunction caused by a dysregulated host response to infection. "In turn, sepsis-induced suppression of the gene encoding chemokine receptor CXCR2 was also reversed by the NTCI peptide." (PMID 41229427, 2025). "At the opposite end of the spectrum of IEI genes induced by sepsis, we found that the most reduced genes are those encoding Nlrp12 (40x), Cxcr2 (35x) and Cr2 (12x)." (PMID 41229427, 2025). "CXCR2 downregulation on neutrophils is implicated in the failure of neutrophil migration toward the infection loci in patients with severe sepsis." (PMID 39253969, 2024). "For CXCR2, this agrees with reportedly reduced sepsis levels of the encoded chemokine receptor at the cell surface, which are also due to activation-induced receptor internalization." (PMID 39434093, 2024). "In severe sepsis, nitric oxide-mediated suppression of CXCR2 is associated with an impaired migration of neutrophils to the infection loci." (PMID 34721400, 2021). "Internalisation of the chemokine receptor CXCR2 was associated with reduced migration in a study of sepsis in mice with alloxan induced diabetes, which is a shared neutrophil dysfunction mechanism common to non-diabetes sepsis models." (PMID 34149714, 2021). "With infection as control, a reduction of CXCR2 surface level is associated with sepsis; its level can be used to distinguish sepsis from infection at the onset of the disease." (PMID 33424860, 2020). "Our study found that, among neutrophil functions studied, only CXCR2 surface level is associated with sepsis." (PMID 33424860, 2020). "A CXCR2-selective antagonist (SB225002) abolishes the protection conferred by PLD2 deficiency during experimental sepsis, suggesting that enhanced CXCR2 expression in neutrophils promotes survival in PLD2−/− mice." (PMID 27721573, 2016). "In contrast to the observation that CXCR2 is internalized in circulating ­neutrophils during severe sepsis, this receptor has been implicated in neutrophil infiltration into the lungs, due to the release of CXC chemokines in this organ during sepsis." (PMID 27199981, 2016). "Corroborating these data, tlr2-, 4-, and 9-deficient mice show an increase in CXCR2 expression on circulating neutrophils, compared with WT mice subjected to severe sepsis." (PMID 27199981, 2016). "In recent years, several studies have described the mechanisms underlying CXCR2 internalization in circulating neutrophils during sepsis, resulting in failure of migration to the infectious focus." (PMID 27199981, 2016). "It has been shown that mice subjected to CLP show deficient neutrophil migration to the site of infection during severe sepsis, which is associated with decreased expression of CXCR2 on the cell surface." (PMID 24667684, 2014). "Downregulation of CXCR2 expression on circulating neutrophils is associated with impaired neutrophil migration to sites of infection during sepsis." (PMID 24755316, 2014). "Existing studies indicate that CXCR2 blockade can mitigate experimental sepsis-associated inflammation and organ damage, yet it may also impair the host’s immune defense against infection." (PMID 41259376, 2025). "Notably, ALKBH5 deletion led to significant suppression of Cxcr2 transcripts in neutrophils, which was consistent with our in vivo observation about decreased CXCR2 protein expression on Alkbh5-deficient peritoneal neutrophils during early stage of sepsis." (PMID 35764614, 2022). "The cell-surface expression of CXCR2 protein was significantly decreased on ALKBH5-deficient dHL-60 human neutrophils infected with E.coli, which was consistent with our in vivo results that loss of ALKBH5 declined CXCR2 protein expression on neutrophils from sepsis mice." (PMID 35764614, 2022). "However, the detailed mechanism underlying the direct regulation of CXCR2 expression on the membrane of neutrophils during sepsis has been poorly investigated." (PMID 30233596, 2018).
Sepsis (continued). "Likewise, experimental studies indicated that alloxan-diabetic mice are highly susceptible to polymicrobial sepsis due to downregulation of CXCR2 in neutrophils, preventing their migration to the focus of infection." (PMID 29780390, 2018). "Similarly, CXCR2, a chemokine receptor, plays a pivotal role in neutrophil recruitment to sites of infection, and its dysregulation has been implicated in the pathophysiology of sepsis." (PMID 41259376, 2025). "Thus, decreased expression of IL-8 receptors (CXCR-1 and CXCR-2) associated with enhanced chemoattractant production during sepsis may impair perception of chemoattractants by PMN and thereby contribute to defective PMN chemotaxis." (PMID 23316483, 2012). "In summary, our study dissects neutrophil heterogeneity in BALF by scRNA‐seq analysis and determines that CXCR2+ neutrophils are a key subpopulation involved in immunosuppressive phase of sepsis." (PMID 39887584, 2025). "A separate group reported that down-regulation of CXCR2 on neutrophils prevents migration to the site of infection during severe sepsis." (PMID 40977737, 2025). "Surprisingly, IL-27 receptor KO pups displayed increased levels of CXCR2 in the spleen during sepsis." (PMID 40977737, 2025). "We also observed the similar finding of decreased CXCR2 expression levels in the spleen of WT pups during sepsis." (PMID 40977737, 2025). "CXCR2+ neutrophils is highlighted as a contributor to septic immunosuppression and a potential therapeutic target in sepsis." (PMID 39887584, 2025). "Here, we explored the mechanism by which elevated levels of CXCR2 aid in combating sepsis in IL-27Rα KO neonatal mice." (PMID 40977737, 2025). "Analysis of the transcriptome of the neonatal spleen during Escherichia coli-induced sepsis in IL-27Rα KO mice identified elevated expression of the chemokine receptor gene CXCR2." (PMID 40977737, 2025). "Inhibit the expression of MDSC CCR2 and CXCR2 to suppress the aggregation of MDSCs and improve the survival rates of sepsis mice." (PMID 40153575, 2025). "The excessive TLR4 signaling promotes a failure of neutrophil recruitment to infected tissues due to CXCR2 internalization during sepsis." (PMID 40241761, 2025). "After sepsis, CXCR2 on the surface of neutrophils undergoes intracellular translocation, leading to the inhibition of neutrophil migration, and G protein-coupled receptor kinase (GRK) plays an important role in this process." (PMID 40153575, 2025). "Taken together, the CXCR2+ neutrophil subpopulation is discovered as a contributor to immunosuppression in sepsis and identified it as a potential therapeutic target in sepsis treatment." (PMID 39887584, 2025). "Neutrophils with high CXCR2 expression levels are recruited to the liver and guided along the concentration gradient of chemoattractant signals later in sepsis." (PMID 40092997, 2025). "In mice and patients with severe sepsis, the expression of the neutrophil canonical chemokine receptor CXCR2 has been shown to internalize in circulating neutrophils, which is associated with the impaired migration of these cells to the infection focus." (PMID 40241761, 2025). "The activation of Toll-like receptors (TLRs) in neutrophils downregulates CXCR2 expression and impairs neutrophil migration in sepsis." (PMID 39062109, 2024). "Only the cell membrane protein encoding genes CXCR2 and CEACAM4 were more highly expressed in SIRS than sepsis." (PMID 39434093, 2024). "The literature indicates that TLR4 plays a crucial role in neutrophil migration during sepsis, influencing neutrophil movement through the regulation of CXCR2 expression." (PMID 39455728, 2024). "In this study, we reveal a previously unproven phenomenon and mechanism in which sepsis-activated microglia induces the occurrence of neuronal ferroptosis via the CXCL2/CXCR2/Jun axis." (PMID 40115159, 2024).
Sepsis (continued). "CXCR2 is induced on the surface of neutrophils in a TLR2 or TLR4-dependent manner in patients with sepsis and mediates neutrophil infiltration into important organs such as the lungs, hearts, and kidneys." (PMID 36891309, 2023). "Decreased neutrophil CXCR2 expression in sepsis patients correlates with the Apache II score, a parameter for disease severity." (PMID 37048076, 2023). "The close connection of CXCL8 and CXCR2 to sepsis onset and progression makes them biomarkers and therapeutic targets worth exploring." (PMID 36451225, 2022). "Thus, the dosed interference with CXCR2 signaling may be a promising target for modulating the early and late dysregulated immune response that protects the liver from injury and failure during sepsis, associated with poor short, mid and long-term survival." (PMID 36451225, 2022). "In contrast, activating CXCR2 via the extracellular matrix degradation product acetylates Pro-Gly-Pro protected mice from severe sepsis." (PMID 36451225, 2022). "Based on the distinct stage of sepsis, CXCR2 expressing neutrophils have various functions throughout the diseases." (PMID 36451225, 2022). "Inducible nitric oxide synthase (iNOS) attenuates CXCR2 internalization and restores its function in sepsis." (PMID 36451225, 2022). "The expression of surface CXCR2 on neutrophils is widely considered a sepsis-specific biomarker that correlates to sepsis’s clinical severity and mortality." (PMID 36451225, 2022). "And TNF inhibits neutrophil migration to the peritoneum in response to polymicrobial sepsis by decreasing CXCR2 expression and inducing apoptosis." (PMID 35819838, 2022). "Firstly, XBJ effectively reversed lung injury caused by sepsis and restrained neutrophils recruitment to lung by down-regulating proinflammatory chemokines, such as CSF-3, CXCL-2, and CXCR-2." (PMID 36467039, 2022). "In contrast, severe chronic stages of sepsis show endothelial barrier damage leading to immature neutrophils with lower expression of CXCR2 entering the bloodstream." (PMID 36451225, 2022). "The chemotaxis of neutrophils via CXCR2 from the circulating blood to the infection regions plays a vital role in sepsis." (PMID 36451225, 2022). "For the acute stage of sepsis, mature circulating neutrophils in the blood expressing high CXCR2 levels migrate from the bloodstream to the liver via chemoattractant (CXCL) gradients." (PMID 36451225, 2022). "Similar observations with the inhibition of IL-33 elucidate CXCR2 as a promising target in sepsis therapy." (PMID 36451225, 2022). "The counteracting mechanism of CXCR2 internalization has also been identified to overcome sepsis-related receptor suppression." (PMID 36451225, 2022). "CXCR2 downregulation in sepsis depends on its phosphorylation by the G protein-coupled receptor kinase-2 (GRK2) and the upregulation of a serin-threonine protein kinase." (PMID 36451225, 2022). "In sepsis, the frequently occurring initial cytokine storm can desensitize CXCR2 early, incapacitating immune cells to migrate to the side of infection efficiently and reducing the regenerative capacity of non-immune cells essential for liver regeneration." (PMID 36451225, 2022). "Neutrophil CXCR2 was higher in iRHOM2−/− mice but declined to similar levels as wild-type mice after sepsis." (PMID 35723764, 2022). "As the levels of the two chemokines are increased in obesity/obese mice desensitization of CXCR2 (homo- or heterologous GPCR desensitization) during sepsis cannot be excluded." (PMID 33673387, 2021). "IL-33 controls neutrophil recruitment during sepsis by preventing downregulation of CXCR2 and inhibition of chemotaxis induced by the activation of TLR4 in mouse and human neutrophils." (PMID 33673387, 2021).